MMP9 (matrix metallopeptidase 9)
Diseases named in the same sentence as MMP9 in open-access papers (continued):
Sharing a sentence is not in itself a finding about the gene and the disease.
tumor (continued). "Upregulation of MMP-9 augments the abnormal proliferation, migration, and invasion of GBM cells, thereby contributing to tumor metastasis in the mouse lung." (PMID 29029486, 2017). "After MMP9 knockdown, lungs from mice that received 3T3-EXO- or 3T3-A-EXO-treated 3LL cell transfer exhibited similar tumor foci and weights." (PMID 29137230, 2017). "Another pathway is related to genetic changes, which induce reconstruction of tumor microenvironment, resulting in expression of pro-tumorigenic factors involving IL-6, IL-8, VEGF, or MMP9." (PMID 28212583, 2017). "We have shown that MMP9 has a contrasting protective role in CAC in the setting of chronic inflammation and, acts as a tumor suppressor in CAC." (PMID 29212256, 2017). "As a MMP-9 inhibitor, ATIQCTPC inhibited the metastasis of LLC, and slowed the growth of the primary tumor of LLC implanted C57BL/6 in mice." (PMID 28969037, 2017). "Matrix metallopeptidase 9 (MMP-9), another factor, important in metastatic potential of tumor cells, was also strongly downregulated." (PMID 28620146, 2017). "Neutrophils have been reported to promote tumorigenesis and progression by secreting tumor growth factors such as vascular endothelial growth factor (VEGF), hepatocyte growth factor, elastase, and MMP9." (PMID 28498842, 2017). "Using primers specific for human gene transcripts, the relative gene expression was determined in the tumor, and by using mouse-specific primers, contribution from the stromal cells was analyzed for TGF-β1, MMP-9 and MMP-2." (PMID 28819116, 2017). "The presence of IL-8 CXC receptors in tumour cells increases ERK phosphorylation and MMP-7 and MMP-9 release, representing a tendency to proliferation, migration, and invasion." (PMID 28381274, 2017). "HSYA from Honghua was validated to antagonize tumor angiogenesis by inhibiting the protein expression of VEGFA, MMP9 and HIF1A4." (PMID 28074863, 2017). "Western blot analysis showed that VEGF, MMP9, and phosphorylated SYK protein in tumor tissues of the nude mice decreased with increasing dosage of piceatannol, which was consistent with the in vitro assay." (PMID 29137391, 2017). "Our results suggest LIUS and DOX combination treatment suppresses tumor growth, prolongs survival, increases the expression of MMP-2 and MMP-9, and promotes the deposition of collagen fibers in OSCC xenograft." (PMID 29157266, 2017). "Nevertheless, OSCC cells and TAMs together through IL-1β/IL-1R and CXCR4/ SDF-1α and via activation of the ERK signalling pathway produce tumour cell migration and invasion by inducing expression of matrix metalloproteinase (MMP) enzymes MMP-9 and MMP-13." (PMID 28381274, 2017). "Since EMT is also associated with the acquisition of migratory and invasive properties of tumor cells, we also examined the expression of MMP-2 and MMP-9." (PMID 28801561, 2017). "Some studies suggest that the PI3K/AKT signaling pathway can promote tumor invasion and metastasis by controlling the expression of MMP-2 and MMP-9." (PMID 29157266, 2017). "Due to the common characteristic invasive behaviour of trophoblast cells and tumour cells, the molecular pathways (MMP2/MMP9) of these two types of cells are strikingly similar." (PMID 28032589, 2017). "MMP-2 and MMP-9 are known to degrade the BM and ECM, and this degradation facilitates migration and invasion of tumor cells." (PMID 29157266, 2017). "In turn, these myeloid cells stimulate tumor vascularization and metastasis by secreting metalloproteinase MMP9/gelatinase-B, which increases recruitment of endothelial cells and pericytes." (PMID 28977919, 2017). "MMP2, MMP9 and FN1 (Fibronectin 1) play important roles in tumor metastasis and are closely correlated with the migration and invasion of tumor cells." (PMID 29100277, 2017). "MMP2, MMP9, and MMP13 are the main members of the MMPs family and had been reported to play a key role in tumor migration and remote metastasis in HCC and other cancers." (PMID 28959024, 2017).
tumor (continued). "MMP2 and MMP9 belong to MMP family, which have important roles in tumor cell invasion and metastasis." (PMID 28388883, 2017). "Increased MMP3 protein levels were noted in tumor tissues from obese patients, and MMP3 protein levels were positively correlated with MMP9 activities." (PMID 29137230, 2017). "MDSCs promote tumor metastasis and angiogenesis via secreting VEGF and MMP9 which is also regulated by IL6-STAT3 activation." (PMID 29142311, 2017). "Previous studies have shown that tumor growth and angiogenic factors including bFGF, NRG2 and MMP9 promote EMT during tumorigenesis." (PMID 28514754, 2017). "UA induces the release of apoptosis factors from mitochondrion in M4Beu cells and inhibits tumor progression, tumorigenesis and angiogenesis through the suppression of lipoxygenase, COX-2, MMP-9 and NOS expressions." (PMID 29228621, 2017). "Collected the tumor tissues were subjected to western blot showed decreased protein expression of pSTAT3 ser727, total STAT3, Bcl-2, Bcl-XL, FAS, cyclin D2, MMP2, and MMP9 in metformin treated vs. control mice." (PMID 28114390, 2017). "In breast cancer cell line MDA-MB-231, AST-IV inhibited the viability and invasion of tumor cells, downregulated the expression of Vav3, MMP-2, and MMP-9 through suppressing the activation of ERK1/2 and JNK." (PMID 29344421, 2017). "The cooperation of RhoA/MMP-9 and Cdc-42/MT1 MMP pathways can form invadopodia of tumor cells activated by nuclear S100A4." (PMID 29069865, 2017). "Our results showed that mollugin suppressed not only the expression of MMP-9 and ICAM-1, but also the expression of VEGF, which are major mediators of tumor cell angiogenesis." (PMID 28933726, 2017). "After fusion with tumor cells, adipocyte-derived exosomes transfer MMP3 into tumor cells and enhance the invasive ability of tumor cells by activating MMP9." (PMID 29137230, 2017). "Inhibition of sorcin expression can down- regulate the expression of CTSZ, MMP2, MMP9 and p-STAT3 followed by suppression of tumor growth and metastasis." (PMID 29262638, 2017). "IHC analysis of xenograft tumor showed HN1 overexpression enhanced MMP9 expression, and knockdown of HN1 inhibited MMP9 expression." (PMID 28490334, 2017). "To validate our findings regarding CNVs identified by CNVpanelizer, we investigated SOX11, CDX2, MMP9, CARD11 and EDEM2 copy numbers in 41 tumour sections by gene-specific FISH." (PMID 28120820, 2017). "The present finding is consistent with previous reports that MMP-9 overexpression in OSCC cells increased cell migration and invasion in vitro and tumor growth and lymph node metastasis in vivo." (PMID 29137326, 2017). "To further investigate the expression and clinical significance of Rab1B and MMP9 protein in CRC, we collected 179 pairs of cancer and corresponding adjacent non-tumor tissues from CRC patients." (PMID 28316326, 2017). "The expression of MMP-9 and MMP-2 is considered an important sign of tumor invasion due to the critical roles the basement membrane plays in the process of tumor invasion." (PMID 29312615, 2017). "MMP-2 and MMP-9 can specifically degrade the type IV collagen which is the dominant component in ECM, facilitating tumor cell migration and metastasis." (PMID 29050226, 2017). "Once in tumors, TANs release factors such as oncostatin M that induce tumor cells to produce VEGF and matrix metallopeptidase 9 (MMP9) to facilitate angiogenesis." (PMID 28467800, 2017). "In co-cultures with MDA-MB-435 and fibroblasts, the tumor cells showed a significant increase in TGF-β type 1 and type 2 receptors and MMP-9 expression." (PMID 28819116, 2017). "Tumor conditions down regulate C/EBPα in MDSCs, which leads to elevated expression of VEGF and MMP9 as well as increased angiogenesis." (PMID 29070836, 2017).
tumor (continued). "We further determined the activity of MMP-9 and MMP-2 which are considered to be most crucial markers in tumor invasion due to their ability to degrade the extracellular matrix (ECM)." (PMID 29299144, 2017). "It’s reported that EMMPRIN and MMP-9 can be found in normal keratinocytes and tumor cells and the expression of EMMPRIN is much higher in tumor tissues than the adjunct normal tissues." (PMID 29137291, 2017). "After the sustained expression of IL-35 in vivo, neutrophils produced more MMP-9 and Bv8 that promote tumor angiogenesis and iNOS that inhibits T cell activation, but expressed much less TRAIL that induces tumor cell apoptosis and inhibits angiogenesis." (PMID 28432279, 2017). "As expected, we also observed tumor‐promoting factors (TGFβ, VEGF, MMP‐2, MMP‐9, and HIF‐1α) were reduced in BDM‐treated groups compared with the control animals." (PMID 28211615, 2017). "Anyway, MMP-9 increases following brain surgery, suggesting that increases in the serum level of this protein may be associated with brain inflammation and breakdown of blood brain barrier rather than be a true measure of tumor burden." (PMID 27757720, 2017). "This impaired tumor growth, the migration and invasion of the cells, and MMP-2, MMP-9, integrin β1 and Bcl-2 were involved in these processes." (PMID 28350359, 2017). "The formation of new blood vessels contributes to tumor growth and is under the regulation of important proangiogenic factors such as MMP-2 and MMP-9." (PMID 29238715, 2017). "LRP1 not only regulates tumor invasion and migration through metalloproteinase MMP-2 and MMP-9 expression, but it also inhibits cell apoptosis by affecting caspase-313." (PMID 29138479, 2017). "Neutrophils express also high levels of metalloproteinases, mainly MMP9, which can modify the ECM to allow tumor cell dissemination." (PMID 29340117, 2017). "The objectives of the study were to assess the relationship between the serum levels of MMP-9 and NGAL and the clinical staging and histopathological grade of the tumor." (PMID 29089666, 2017). "We also evaluated the effect of Rhy on the expression of CXCR4, MMP-9, and MMP-2, proteins which play a critical role in tumor metastasis." (PMID 28534824, 2017). "In support of an anti-tumor role for MMPs, treatment with the MMP inhibitor tanomastat, which has selective activity against MMP2, MMP3 and MMP9, was shown to lead to a worse outcome compared to standard treatments." (PMID 26956475, 2016). "Due to their broad distribution in the human body and wide range of hydrolysis substrates, MMP-2 and MMP-9 are regarded as key enzymes for hydrolyzing the ECM and promoting tumor invasion." (PMID 27716341, 2016). "MMP-9 level was evaluated in the serum in 5 studies by ELISA, 21 studies used immunohistochemistry to detect MMP-9 and 1 study used a PCR method to assess the MMP-9 level in tumor tissue homogenate." (PMID 26918342, 2016). "Matrix metalloproteinases (MMPs), such as MMP9, mainly produced by neutrophils, have the ability to degrade the extracellular matrix (ECM), which contribute to carcinogenesis and tumor progression." (PMID 27446967, 2016). "Tumor cells are reported to secret huge amounts of MMP2 and MMP9 in a paracrine or autocrine manner to stimulate their invasion and migration." (PMID 27034162, 2016). "Following the Smad signaling mediators, the down-regulation of AR consequentially activated target genes like matrix metallopeptidase 9 (MMP-9) and promote tumor metastasis." (PMID 27703473, 2016). "Our animal study revealed that HEGU inhibited the expression of Ki67, CD45, CD31, VEGF-A, HIF-1α, iNOS, and COX-2 in tumor tissues and plasma levels of VEGF-A, MMP-9, ICAM, and VACM." (PMID 27314329, 2016). "Other adipocyte-secreted factors, such as MMP9 and IL8, have been shown to have tumor-promoting effects." (PMID 27705905, 2016). "In studies of human tumor angiogenesis, VEGF and MMP9 levels have been shown to correlate, with each able to potentiate the other." (PMID 26863115, 2016).
tumor (continued). "We found that PER1 knockdown not only increased MMP2 and MMP9 expression, but also decreased TIMP-2 expression, presumably leading to the observed increases in tumor cell migration and invasion." (PMID 26943040, 2016). "Quantitative RT-PCR was used to determine the expression of TNF, COX2, MMP9 and CTNNB (catenin beta) in tumor samples." (PMID 27323816, 2016). "Moreover, MMP-3 may activate the expression of MMP-9 in tumor cells." (PMID 26510742, 2016). "As we know, matrix metalloproteinase is necessary molecular during the tumor metastasis, particularly the MMP2 and MMP9." (PMID 26883105, 2016). "MMP14 enhances tumor invasion and dissemination through cleavage of CD44, a cell surface glycoprotein, or activation of MMP-2 and MMP9 through a combination of TIMP-2 and MMP14." (PMID 27613828, 2016). "STAT1 negatively regulates angiogenesis, tumorigenicity, and metastasis of tumor cells by inhibiting the expression of bFGF, MMP-2, and MMP-9." (PMID 26928402, 2016). "In this study, the MMP-9 expression was induced by TPA, a potent tumour promoter used for studying cancer metastasis that can induce MMP-9 expression and promote cancer cell metastasis." (PMID 26980735, 2016). "Polarized TAMs influence tumor progression by releasing multiple cytokines, such as VEGF and MMP-9, to sustain angiogenesis and proliferation." (PMID 27367025, 2016). "Although the anti-MMP-9 behavior led TIMP1 to be considered as a tumor suppress gene initially, later, researchers found that TIMP1 also functions independently of MMP-9 to promote tumor growth and inhibit apoptosis." (PMID 26918342, 2016). "In the present work, we demonstrated that Rhus coriaria inhibited the NFκB signaling through downregulation of phospho-p65 as well as its downstream targets (MMP-9, VEGF, IL-6 and IL-8), all of which are involved in tumor metastasis." (PMID 26888313, 2016). "Previous studies have shown that S100A4 expression can upregulate the matrix metalloproteinases (MMPs), which play critical role in tumor metastasis through degradation of extracellular matrix (ECM), including MMP-9, MMP-13, and MMP-2." (PMID 26903691, 2016). "Our results showed that 6 days of treatment with tumour homogenates induced M2 macrophage makers, CD163, IL-10 and MMP9 expression, as well as the expression of legumain in U937 cells." (PMID 27464733, 2016). "AP-2α expression is reduced in advanced CRC tumor tissues as compared to matched normal tissues and loss of AP-2α promotes invasion of CRC through down-regulation of E-cadherin and up-regulation of matrix metalloproteinase 9 (MMP9), indicating that KLF12 may be involved in CRC." (PMID 27442508, 2016). "MMP-9 and MMP-2 are upregulated in all human and animal tumors and their expression is increasing with each and every stage of tumor progression." (PMID 27110764, 2016). "During this tumor invasion and metastasis, several matrix metalloproteinases (MMPs) like MMP-2 and MMP-9 play a critical role by degrading the extracellular matrix and components of the basement membrane." (PMID 27659937, 2016). "In multiple tumor types, MMP-9 drives cell behaviors such as epithelial to mesenchymal transition and invasion, primarily through the effects of MMP-9 on degradation of extracellular matrix such as collagen I, II, and IV." (PMID 27888810, 2016). "The aim of the present study was to evaluate the prognostic value of serum tumor markers, namely CA15-3, CEA, HER2 ECD, NSE, MMP-9 and S100ß in a series of MBC patients." (PMID 27387327, 2016).
tumor (continued). "Since c-Jun and MMP9, which are a major downstream molecule and a target gene in the JNK pathway, were reported to play important roles in JNK-mediated tumor growth and metastasis, we further examined the effect of miR-141 and SPAG9 on these gene expressions." (PMID 26790956, 2016). "MMPs were reported to induce tumor progression in HCC including MMP-1, MMP-2, MMP-3, MMP-7, MMP-9, MMP-11 and MMP-13." (PMID 26882566, 2016). "Among the genes involved in the hepatic fibrosis pathway, expression of the IGFBPs, COL4A1, COL4A2, MMP9 and TNFRSF11B was restored in 143BNSC and 143BGBM tumours." (PMID 27551510, 2016). "Our data also indicated that PS341 treatment largely decreased the expression of both MMP2 and MMP9 in HCC and CRC cells, thus restricting the migration capacities of these two tumor types." (PMID 26915315, 2016). "These cells accumulate in TME and produce factors such as VEGF, matrix metallopeptidase 9 (MMP9), and transforming growth factor beta (TGF-β), which support angiogenesis and tumor growth and eventually invasion and metastases of tumor cells." (PMID 28008330, 2016). "The clinical investigation showed that CLU, MMP-9 and VEGF were positively correlated with the tumor-node -metastasis (TNM) classification." (PMID 26716898, 2016). "Accordingly, overexpression of Par4 inhibits invasion and reduces tumor growth of breast cancer cells by reducing the levels of MMP-2 and MMP-9." (PMID 26872368, 2016). "Several studies reveal that N2 neutrophils express MMP9, NE, and CXCR4, among other pro-tumor mediators." (PMID 27169366, 2016). "MMP-9 can degrade some extracellular matrixs, and the change of MMP-9 expression is closely related to tumor metastasis and invasion in various tumors." (PMID 27806329, 2016). "Our in vitro data further reveals that GC cell lines over-expression Aplein and its receptor APJ, together with the other cytokines which are known to facilitate tumor metastasis and progression, including IL-1, IL6, MMP1, MMP9 and BMP-2." (PMID 27733135, 2016). "The matrix metalloproteinases, MMP-9 and MMP-2 function as key mediators of basement membrane degradation, angiogenesis, tumor invasion in GBM." (PMID 26940200, 2016). "In conclusion, the present study provides evidence that AMOP domain plays the key role in MUC4/Y(MUC4)-mediated tumour angiogenesis and metastasis of PC cells partly through the NOTCH3 signalling and its downstream target genes: VEGF-A, MMP-9 and ANG-2." (PMID 27287498, 2016). "MMP7 and MMP9 induced syndecan 1 and CXCL6 production in tumor cells, which act as chemoattractants for neutrophils and mediate their influx to the tumor microenvironment." (PMID 26956475, 2016). "Since only a limited number of frozen tumor samples were available from BEVERLY-2 patients, we analyzed MMP2 and MMP9 mRNA expression in 137 clinical IBC samples profiled within the World IBC Consortium (E-MTAB-1006, E-MTAB-1547 and GSE22597)." (PMID 26921265, 2016). "We also investigated the role of miR-326 on expression of MMP-7 and MMP-9, which all play a key role on tumor metastasis, and results indicated miR-326 inhibited the mRNA expression of MMP-7 and MMP-9 both in A549 and SPC-A-1 cells." (PMID 26840018, 2016). "The role of these proteins in tumor invasion and metastatic dissemination is largely known as they interact with each other forming the NGAL/MMP-9 complex that in turn promotes the extracellular matrix degradation process necessary for tumor spreading." (PMID 27602581, 2016). "The levels of MMP9 and miR-3713 in 28 pairs of resected TCC tissues (Stage IV) and adjacent non-tumor bladder tissues (NT) were measured by Western blot and RT-qPCR, respectively." (PMID 27577949, 2016). "Staining area and intensity of MMP2 and MMP9 in the MC38 and LLC tumor colonies were notably decreased in the S100A8 and S100A9 knockdown groups compared with controls." (PMID 27086923, 2016).